INS (insulin)
Diseases named in the same sentence as INS in open-access papers (continued):
Sharing a sentence is not in itself a finding about the gene and the disease.
diabetes (continued). "Particularly, the treatment plans used to try to manage diabetes are the use of hypoglycaemic medications, insulin injections, and surgical therapies (bariatric)." (PMID 38069300, 2023). "Diabetes mellitus is a metabolic disorder characterized by increased serum glucose due to errors in insulin production or response." (PMID 36751181, 2023). "All were diagnosed with diabetes before the age of 12 months and needed replacement insulin therapy." (PMID 36704923, 2023). "After entering a hyperglycemic state, NPH insulin was administered to manage insulin-dependent diabetes mellitus." (PMID 38026640, 2023). "Diabetes is a metabolic disease due to the body’s inability to produce insulin or its inability to fully utilize insulin." (PMID 38201125, 2023). "Additionally, the higher annual risk of hypoglycemia in insulin-treated Egyptians with diabetes mellitus (DM) in comparison to other countries, both in type 1 (T1D) and type 2 diabetes (T2D), is another risk factor that needs to be taken into account." (PMID 37867270, 2023). "The first step in the treatment of diabetes is to control serum glucose levels, which can be done in several ways, including the use of antidiabetic medications, physical activity, and insulin therapy." (PMID 36788517, 2023). "The primary pathological process underlying type 2 diabetes mellitus (T2DM) is islet dysfunction, which is characterized by impaired insulin secretion." (PMID 37480086, 2023). "Additional risk factors for rUTI in diabetic patients mentioned across the studies included retinopathy, overactive bladder, incontinence, kidney problems, narrow/blocked arteries, insulin treatment, age, and duration of diabetes." (PMID 40778033, 2023). "Diabetes, particularly in patients taking insulin, has consistently been shown to be an independent predictor of adverse outcomes after DES." (PMID 36975883, 2023). "These protein redox changes activate different downstream signaling pathways that play important roles in impaired insulin secretion and insulin resistance, critical for the onset of diabetes mellitus and its consequences." (PMID 36770960, 2023). "Before diabetes is diagnosed, peripheral insulin sensitivity is often already impacted, and lifestyle-related prevention is especially effective in this prediabetic state." (PMID 37049441, 2023). "More persons with diabetes on insulin expected realistic expectations compared to those on metformin or glyburide (p ≤ 0.01)." (PMID 36817935, 2023). "Rats with experimentally induced diabetes displayed lower peak melatonin levels, pancreatic melatonin receptor overexpression and higher insulin levels during glucose metabolism impairment." (PMID 36974476, 2023). "T1D is a polygenic form of diabetes, an autoimmune multifactorial disorder with impaired insulin production due to pancreatic beta cell destruction." (PMID 37509590, 2023). "An example of this is a patient presenting with dyspnea, polyuria, and polydipsia with a history of diabetes who ran out of insulin." (PMID 37568944, 2023). "Diabetes is a chronic metabolic disease characterized by dysregulation of carbohydrate, lipid and protein metabolism, and results from impaired insulin secretion, insulin resistance or a combination of both." (PMID 38132046, 2023). "Extra-islet and extra-pancreatic IPCs are the spotlight of researchers for at least two reasons: first, they are additional sources of insulin and probably are able to alleviate hyperglycemia and prevent complications of diabetes." (PMID 38019818, 2023). "Long‐term diabetes can lead to changes in the body's sensitivity to insulin, making it more challenging to regulate blood sugar levels." (PMID 40496787, 2023). "Diabetes is a chronic metabolic illness recognized by persistently elevated blood sugar levels resulting from a decrease in insulin synthesis or a rise in insulin resistance." (PMID 37631156, 2023).
diabetes (continued). "Research on a mouse model of diabetes with STZ use has shown that glycaemic control through insulin can contribute to the regeneration of pancreatic β-cells." (PMID 36829539, 2023). "Impaired insulin signaling and increased lipolysis in diabetes leads to increased myocardial fatty acid oxidation (FAO), oxidative stress, and eventually left ventricular dysfunction." (PMID 36835096, 2023). "Tools such as continuous glucose monitors, insulin pumps, and smart pens not only have a positive impact on diabetes management but can also allow telemedicine to become standard practice in this group of patients." (PMID 37685740, 2023). "The aim of this study was to describe appetite and glucose fluctuation in type 2 diabetes mellitus patients initiating treatment with dulaglutide combined with insulin degludec." (PMID 37255975, 2023). "In the past medical history (PMH), the patient had a history of diabetes mellitus with insulin therapy and a left knee joint replacement 1.5 years ago." (PMID 37496037, 2023). "In cancer patients with diabetes mellitus, TKIs reportedly improved glycemic control, allowing insulin discontinuation." (PMID 37592236, 2023). "Children and adolescents with diabetes and their parents or caregivers experience psychological or physical problems, and a factor responsible for this burden is insulin injection-related stress." (PMID 37474582, 2023). "This seems to contradict the known physiology that insulin sensitivity decreases progressively with advancing diabetes and with obesity." (PMID 36848379, 2023). "The original description of the NeuroD1/MODY6 form of diabetes also reported obesity and “relatively high insulin levels” in diabetic members of a family." (PMID 38333726, 2023). "Exercise improves glycemic control, insulin sensitivity, and fatty acid uptake in adipose tissue, skeletal muscle cells, and endothelium in patients with diabetes mellitus." (PMID 37089434, 2023). "Due to the poor impact of insulin on target tissues, diabetes produces abnormalities in glucose, lipid, and protein metabolism." (PMID 37287539, 2023). "Diabetes Mellitus (DM) encompasses a range of metabolic disorders defined by hyperglycemia resulting from defects in insulin secretion, insulin action, or both." (PMID 37873778, 2023). "Zinc is involved in normal insulin synthesis and secretion, and thus in maintaining a normal blood glucose level, and its homeostasis is altered in diabetes." (PMID 37107221, 2023). "The most common feature of diabetes is hyperglycemia, which occurs as a result of impaired insulin secretion or insulin action." (PMID 37424869, 2023). "On the other hand, insulin sensitivity is reduced in several diseases such as diabetes and obesity and the adiponectin level also decreases." (PMID 38004353, 2023). "Since FOXO proteins are key mediators of insulin signaling, they have been suggested as potential therapeutic targets for the treatment of diabetes." (PMID 37891184, 2023). "Patients with diabetes who develop hyperthyroidism should be considered for a modification of their insulin therapy." (PMID 36983604, 2023). "Diabetes duration (P = 0.63), type of insulin delivery (P = 0.48) and glucose monitoring (P = 0.35) were uninfluential." (PMID 36800003, 2023). "In this review, we discuss the critical molecular, cellular, and structural changes to the skin in the hyperglycaemic and insulin-resistant environment of diabetes with a focus specifically on human-derived data." (PMID 37365017, 2023). "The top five clusters of the keyword co-appearance network were “prediabetes”, “diabetes mellitus”, “glucose”, “insulin exercise”, and “oxidative stress”." (PMID 36908460, 2023). "For outpatients, diabetes-specific formulas also improve metabolic control and, in some cases, HbA1c and insulin requirements compared to the use of a standard formula." (PMID 38068834, 2023).
diabetes (continued). "Diabetes mellitus, a chronic metabolic disorder, is characterized by hyperglycemia due to defects in insulin secretion, insulin action, or both." (PMID 37497106, 2023). "While CGM is now recommended for all individuals with insulin-requiring diabetes, significant gaps continue to exist in access and use for individuals with T1D, particularly among low-income and historically marginalized communities." (PMID 36817610, 2023). "Even though the body produces a lot of insulin, cells resist it, making them more vulnerable to diabetes." (PMID 36751233, 2023). "Administration of omega-3 fatty acids has been reported to improve diabetes by regulating lipid metabolism, insulin synthesis, and attenuating oxidative stress and insulin resistance by modulating the expressions of inflammatory and energy metabolism genes." (PMID 37755075, 2023). "Diabetes is a disorder that results when the pancreas is unable to produce the hormone insulin, or when the body is unable to respond to insulin when it is produced, in both cases leading to abnormal levels of blood glucose." (PMID 36830072, 2023). "Defects in β-cell function directly contribute to the development of hyperglycemia in major forms of diabetes due to the singularity of insulin’s role as the only hormone capable of reducing blood glucose." (PMID 36997560, 2023). "MicroRNAs (miRNAs) recently emerged as means of communication between insulin-sensitive tissues to mediate diabetes development and progression, and as such they present a valuable proxy for epigenetic alterations associated with type 2 diabetes." (PMID 37958657, 2023). "Diabetes patients usually have diabetes-specific eating behaviors such as insulin omission or restriction, which cannot be assessed by the general tools." (PMID 36771268, 2023). "It was shown that baicalin given to insulin-resistant GK rats at a dose of 120 mg/kg b.w. was more effective in alleviating many diabetes-related disturbances than 500 mg metformin." (PMID 38203600, 2023). "Decreasing insulin production can result in a common medical condition termed diabetes mellitus (DM)." (PMID 37218773, 2023). "The development of resistance to insulin is a common feature of type 2 diabetes mellitus and can also be attributed to the dysfunction of mitochondria." (PMID 37109219, 2023). "One component of the package of support available for CYP is that provided by diabetes technology, namely insulin pumps and continuous glucose monitoring (CGM), including apps that can be downloaded onto a mobile device." (PMID 38136135, 2023). "Diabetes mellitus (DM) is a metabolic disorder resulting from impaired insulin secretion, or a combination of insulin resistance and inadequate insulin secretion." (PMID 37836571, 2023). "The current treatment of diabetes mellitus, which supposes patients self-injection with insulin, has the disadvantage of limited accuracy in blood glucose control and frequent injection." (PMID 36771883, 2023). "The compromised signaling hinders insulin's capacity to effectively facilitate glucose uptake in peripheral tissues, leading to hyperglycemia, a prominent feature of diabetes." (PMID 37868469, 2023). "In the context of diabetes, self-management encompasses daily insulin administration, blood glucose monitoring and maintenance, dietary care, physical activity, embracing a healthy lifestyle with diabetes, and preventing complications." (PMID 38666044, 2023). "Six different clinical scenarios have been identified: type 1 diabetes, type 2 diabetes, pregnancy on intensive insulin therapy, regular physical exercise, new onset of diabetes, and frailty." (PMID 37676398, 2023). "This disease is divided into type 1 diabetes mellitus [T1DM] (resulted from insulin deficiency) and type 2 diabetes mellitus [T2DM] (resulted from resistance towards insulin)." (PMID 37365646, 2023). "As part of insulin treatment, achieving good glycemic target requires a comprehensive diabetes education." (PMID 37777715, 2023).
diabetes (continued). "The gradual malfunction of the β-cells and the reduction in their number due to apoptotic death, lead to a decrease in insulin production and thus to hyperglycemia and diabetes." (PMID 36835101, 2023). "Choi and Kim also confirmed that the administration of oral hypoglycemic agents or insulin had a significant effect on diabetes distress." (PMID 37893847, 2023). "This integration of CGM and insulin delivery into a single device can help maintain more stable blood glucose levels, potentially reducing the burden of diabetes management." (PMID 38239544, 2023). "Prior research has found that adults with T1D and obesity who participated in a BLI for adults with diabetes demonstrated significantly reduced body weight, HbA1C, and total insulin doses prescribed compared to a matched usual care control group." (PMID 37614408, 2023). "A thorough examination of the financial implications of implementing telemedicine for insulin-treated diabetes is essential for informing healthcare decision-makers." (PMID 38077677, 2023). "Bei Patienten mit Typ‐2 Diabetes die mit Insulin behandelt werden scheint, so wie bei Patienten mit Typ‐1 Diabetes, eine höhere Intensität der BZSK, gemessen an der Zahl der täglichen Kontrollen, mit einem niedrigeren HbA1c assoziiert zu sein." (PMID 37101035, 2023). "Hyperglycemia due to abnormalities in insulin secretion, insulin action, or both characterize the metabolic condition known as diabetes mellitus (DM)." (PMID 37370932, 2023). "A clear example of a successful application can be found in the field of diabetes, where insulin subcutaneous infusion in an artificial pancreas system is adapted learning from continuous glucose monitoring in patients affected by type 1 diabetes." (PMID 37685946, 2023). "In fact, some patients require only a strict diet, while others show improvement with oral diabetes medications and/or insulin." (PMID 38162681, 2023). "People with type 1 diabetes mellitus (T1DM) are unable to produce sufficient insulin, whereas people with type 2 diabetes mellitus (T2DM) suffer from end-tissue resistance to the effects of insulin." (PMID 36761187, 2023). "The potential to be less dependent on insulin treatment and to prevent diabetes complications opens up a new and promising time horizon that has been limited in the past." (PMID 37492440, 2023). "Euglycemic diabetic ketoacidosis is a rare but serious side effect of SGLT2 inhibitor treatment, occurring mainly in diabetes with insulin deprivation, after surgery or under infectious conditions." (PMID 36166185, 2022). "The factors that showed differences in health variables in the general and the high-risk group for adolescent diabetes were SBP, FPG, HbA1c, insulin, TG, and uric acid." (PMID 36010139, 2022). "IR can disrupt glucose metabolism, leading to compensatory increases in β-cell insulin production and hyperinsulinemia, which in turn leads to diabetes and other metabolic diseases closely related to CVD and CAC." (PMID 36357872, 2022). "Statistical analysis revealed that the expression of CD34 was negatively correlated with the number of insulin-labeled islet β-cells during diabetes progression in dose-dependent fashion in alloxan-induced diabetes models." (PMID 36467676, 2022). "This loss, mimicked in mice with β cell–specific deletion of FIT2 (βFIT2KO), resulted in reduced β cell LD numbers and diet-induced diabetes, with exacerbated glucose intolerance due to a reduced insulin secretory response." (PMID 35254894, 2022). "After GQD or metformin treatment, although the insulin positive cells were still scattered in the islet, the shape of the islet was enlarged compared to the diabetes group, the cells in the islet were tightly packed (dotted line)." (PMID 35858880, 2022). "Diabetes mellitus is a frequent endocrine disorder characterized by hyperglycemia, hyperinsulinemia, the dysfunction of insulin production and insulin sensitivity." (PMID 35682790, 2022).
diabetes (continued). "Type 1 diabetes mellitus (T1D) is a chronic inflammatory illness, which results from a complete destruction of insulin-producing β-cells as an outcome of the combined action of autoreactive T lymphocytes, inflammatory cytokines and monocytic cells." (PMID 36012972, 2022). "The centenary of insulin discovery represents an important opportunity to transform diabetes from a fatal diagnosis into a medically manageable chronic condition." (PMID 35794109, 2022). "In both genders, CNTF levels correlated significantly and positively with obesity (BMI, WHR, leptin), diabetes (fasting insulin, HOMA index and HbA1c) and inflammation (IL-6 and hsCRP) indices." (PMID 35585213, 2022). "Compared to the Diabetes-β-Cell-Failure group, AUC for both glucose and insulin responses during the OGTT were significantly greater in the Diabetes-Insulin-Resistance group (P < 0.001)." (PMID 36211668, 2022). "In particular, over the past century, nutrition applied with pumps for the administration of insulin and continuous glucose monitoring have allowed substantial advancement in the treatment of type 1 diabetes mellitus." (PMID 36432570, 2022). "He had run out of insulin after his discharge from the hospital, and his diabetes had been complicated by significant pain in his hands and feet which was concerning for diabetic neuropathy." (PMID 36540432, 2022). "Insulin plays a role in managing blood sugar and preventing diabetes complications by keeping blood sugar in the target range (normal or near-normal glycemia)." (PMID 36411933, 2022). "The distribution and analysis of HbA1c, TAS, lipid profile, insulin, diabetes fatigue, and health related quality of life." (PMID 36048792, 2022). "Background and Objectives: Insulin and oral hypoglycemic agents are drugs widely used in the world population due to their therapeutic effects on diabetes mellitus." (PMID 36359343, 2022). "Despite various antidiabetic drugs being used in the management of diabetes, exogenous insulin remains the gold standard treatment for type 1 diabetes." (PMID 35140800, 2022). "Diabetes is theresulting metabolic disorder of diminished production, bioavailability,and sensitivity of insulin against pathologically increased plasmaglucose level." (PMID 35349261, 2022). "Diabetes duration, insulin therapy, fundoscopic examination of the eyes and the neuropathy disability score were assessed." (PMID 35460036, 2022). "Another application is P(3HB-co-3HHx) nanoparticles filled with an insulin phospholipid complex to make a form of insulin that has a long-acting release to treat diabetes." (PMID 36545679, 2022). "One of the current hot research topics is investigating the role of AhR activation by environmental pollutants on glucose homeostasis and insulin secretion, and hence the pathogenesis of diabetes mellitus." (PMID 36418969, 2022). "These individuals were significantly older, with a higher median HbA1c, higher need for treatment under insulin and a higher rate of diabetes‐related complications." (PMID 35822264, 2022). "Alirocumab improved artery mechanical properties in insulin-treated patients with type 2 diabetes mellitus." (PMID 35454151, 2022). "Currently, two different injectable therapies are available for diabetes, one is insulin and the other is glucagon-like peptide-1 receptor agonist (GLP-1 RA), which is a relatively new class of glucose-lowering medications." (PMID 36559020, 2022). "In addition, compared to adults, diabetes has a more aggressive clinical course in children and adolescents, marked by a muted response to current interventions, as well as faster loss of β-cell function, progression of insulin resistance, and development of end-organ complications." (PMID 34913986, 2022). "Those receiving simultaneous insulin and oral hypoglycemic agents for the treatment of diabetes had relatively worse glycemic control, indicating a more aggressive nature of the disease." (PMID 36253738, 2022).